HIF1A (hypoxia inducible factor 1 subunit alpha)
Diseases named in the same sentence as HIF1A in open-access papers (continued):
Sharing a sentence is not in itself a finding about the gene and the disease.
tumor (continued). "Further analysis of each treatment arm separately indicated that lower HIF-1α percent of tumor expression was statistically significantly associated with improvements in both TTP and PFS in the Schedule 4/2 group; however, these associations were not statistically significant in the CDD group." (PMID 25100134, 2014). "Many well-known effects of 2-DG other than glycolytic inhibition like UPR response, N linked glycosylation; HIF-1α etc. may actually facilitate the immune activation in the peripheral blood of tumor bearing mice by the combined treatment (2-DG + radiation)." (PMID 25248151, 2014). "Relationships between RBP2 protein expression and clinicopathologic factors were examined by the chi-square test and our data showed that RBP2 overexpression was associated with tumor size (P = 0.030), high HIF-1α expression (P = 0.028) and high VEGF expression (P = 0.048)." (PMID 25162518, 2014). "In addition, hypoxia and HIF1A induce differentiation of infiltrating MDSC into tumor-associated macrophages." (PMID 25294811, 2014). "Previous researches have shown that PKM2 may be induced by transcription factors, such as HIF-1α, while a number of genes associated with cell proliferation, metabolism, and tumor growth are downstream targets of PKM2." (PMID 24895527, 2014). "Furthermore, the hypoxia-inducible factor 1α (HIF-1α) is an important transcription factor, which is closely associated with the process of tumor growth." (PMID 25013467, 2014). "Recent studies have shown that the percentage of CD44 positive cells expressing variant exons v6 (CD44v6) in tumor cells could be significantly increased by HIF-1α-mediated transcription under hypoxic conditions." (PMID 24647137, 2014). "Finally, we used our model to simulate the effects of known mutations of HiF-1α pathways in tumor cells." (PMID 25338163, 2014). "Similarly, the expression level of HIF1α was significantly higher in tumor tissue than in the corresponding non-tumor lung tissue and was associated with a shorter survival time in NSCLC." (PMID 24567056, 2014). "The aggressiveness of malignant tumors may be caused by aberrant glucose metabolism induced by HIF-1α because several of the glycolytic enzymes are important regulators of tumor cell death and apoptosis." (PMID 23135628, 2013). "Moreover, the Western blotting data revealed that antagomir-21 inhibited tumor angiogenesis through suppressing HIF-1α/VEGF/VEGFR2-associated signaling pathway." (PMID 23951172, 2013). "Tumor cells subjected to hypoxia tend to be more aggressive, displaying increased metastasis, invasion, and mutation; in OS specifically, higher levels of hypoxia inducible factor 1-alpha (HIF-1α) are associated with high-grade lesions and enhanced tumor cell growth in vitro." (PMID 23914349, 2013). "HIF-1α, also known as hypoxia-inducible factor-1α is a hallmark of tumor hypoxia." (PMID 23799043, 2013). "Immunohistochemistry for the HIF1α-inducible proteins CA9 and Glut1, and for HIF1α itself, revealed moderate or strong expression of at least one of these markers in all but two of the tumours, verifying the well-described hypoxic signature associated with loss of function of pVHL." (PMID 23606570, 2013). "Hypoxia is present in a wide range of solid tumors and is often associated with tumor glycolysis, angiogenesis, and poor prognosis, as well as invasion and metastasis by activating relevant gene expression through hypoxia inducible factor-1α (HIF-1α)." (PMID 23927384, 2013). "HIF-1α overexpression induces tumor invasion and is associated with the repression of E-cadherin." (PMID 23946798, 2013). "Interestingly, recent report indicates that overexpression of caveolin-1 in the cancer-associated fibroblasts causes induction of their senescence and supports tumor growth due to HIF-1α stabilization by ROS increase." (PMID 23945296, 2013).
tumor (continued). "Thus, to deeply explore the effect of mutated fibroblasts on surrounding tumour cells we investigated the transcriptional levels of some HIF1α target genes in fibroblasts cultured in hypoxic conditions." (PMID 22272371, 2012). "HIF-1α overexpression is associated with angiogenesis and tumor cell proliferation and invasion." (PMID 22952803, 2012). "It was also recently suggested that HIF1α may function as a tumor suppressor gene in VHL-deficient clear cell kidney cancer." (PMID 23178531, 2012). "In studying how endothelial HIF response itself affects metastasis, we found that loss of HIF-1α in endothelial cells reduces NO synthesis, retards tumor cell migration through endothelial layers, and restricts tumor cell metastasis, and that loss of HIF-2α has in each case the opposite effect." (PMID 22264788, 2012). "This process of “survival” growth may facilitate further tumour growth by causing localised intratumoral hypoxia which is a powerful stimulus to HIF-1α production and therefore more neovascularisation." (PMID 22720169, 2012). "VEGF inhibition causes hypoxia, induces HIF-1α expression and the formation of VM, which may be associated with tumor invasion and metastasis." (PMID 22357313, 2012). "HIF-1α over-expression has been detected in various tumors including breast, oropharyngeal, nasopharyngeal, prostate, brain, lung, stomach cancer and so on, and has been associated with tumor aggressiveness, vascularity, treatment failure and mortality." (PMID 22453051, 2012). "RCC is characterized by high intra-tumour VEGF production by homozygous mutations in the von Hippel-Lindau tumour suppressor gene with consequent unlimited activity of the hypoxia inducible factor 1α (HIF1α) causing high VEGF transcription." (PMID 21637343, 2011). "Recent evidence also suggested that VCP and/or its associated co-factors are also implicated in the direct regulation of HIF1α (hypoxia-inducible factor 1α; tumor angiogenesis and metastasis promoter), Nrf2 and Aurora B kinase (implicated in genomic instability)." (PMID 22216170, 2011). "For instance, inhibitors of mTOR (some of which are already approved for cancer treatment) decrease the level of HIF-1α, and it has been suggested that their efficacy might be assessed by their ability to reverse tumour-associated 18FDG uptake." (PMID 21612605, 2011). "Our data reveal another mechanism through which miR-22 might act as a tumor suppressor: loss of miR-22 expression not only permits an increase in MYCBP but also an increase in HIF-1α." (PMID 21629773, 2011). "Presence of perinecrotic HIF-1α expression was significantly associated with high-grade tumours." (PMID 20565904, 2010). "Additionally, fumarate hydratase (FH) encodes a protein that is an enzymatic component of the tricarboxylic acid (TCA) cycle and its deactivating mutations lead to high level of HIF-1α and tumor formation." (PMID 20824128, 2010). "HIF-1α-positive staining was associated with the histological cell type, being mainly expressed in non-adenocarcinoma subtypes (P<0.001) and in poorly differentiated tumours (P=0.0001)." (PMID 20461082, 2010). "IDH1, encoding two TCA enzymes, fumarate hydratase (FH) and succinate dehydrogenase (SDH), has been found to sustain loss-of-function mutations in certain human tumors, which likewise contribute to tumor growth via stimulating the HIF-1a pathway and mutationally altering metabolic enzymes." (PMID 20459648, 2010). "Overexpression of HIF-1α has been found in many human cancers, including colon, brain, breast, gastric, lung, skin, ovarian, prostate, renal, and pancreatic carcinoma, and is associated with poor prognosis and failure of tumor treatment." (PMID 21179202, 2010). "Hypoxia inducible factor 1α (HIF-1α) is a potential marker of carcicnogenesis since it is overexpresssed in many human cancers such as brain, breast, and uterus, and its role has implicated in tumor cell growth and metastasis." (PMID 32038837, 2009).
tumor (continued). "Nuclear HIF-1α and pVEGF-C expression was associated with lower nuclear grade and smaller tumor size indicating better prognosis, while cHIF-1α together with dVEGF-A and -C was associated with worse prognostic factors, i.e. higher nuclear grade, larger tumor size and higher tumor stage." (PMID 19302703, 2009). "HIF-1α and hypoxia have been shown to be implicated in tumour progression." (PMID 19587783, 2009). "Since the acquisition of metastatic phenotype is a multistep event, the HIF-1α associated perinecrotic processes of both tumor cell survival and death and LPS-mediated inflammatory response could indirectly contribute to this endpoint." (PMID 18983642, 2008). "Thus, the elevated transactivation capacity of variant forms of HIF-1alpha has implied a role of HIF-1α polymorphisms in generating individually different tumor progression profiles." (PMID 16412252, 2006). "This could show a defective HIF1α pathway, or tumour and gene polymorphism differences in the regulation of individual genes." (PMID 12942121, 2003). "p16ink4A and HIF-1α proved to be unrelated to all the investigated variables, whereas a direct association was found between number of metastatic lymph nodes and tumour size or ER (P=0.008 and P=0.01, respectively) and between tumour size and TLI (P=0.05)." (PMID 12402149, 2002). "For HIF1A, known as a hypoxia-inducible transcription factor, copy number variation was modestly linked to neutrophil and dendritic cell infiltration, indicating partial regulation of innate immune responses within the tumor microenvironment by hypoxic signaling." (PMID 41465546, 2025). "Exosomes, linked to tumor metastasis, are secreted in the hypoxic microenvironment and enriched with miRNA-301a-3p, phosphatases, and the angiotensin II/PI3Kγ signaling pathway, which induce HIF1-α or HIF2-α to stimulate M2 macrophage polarization, thereby promoting tumor cell metastasis." (PMID 40443678, 2025). "Additionally, AsA-deficient cells may exhibit increased HIF-1α activity, potentially contributing to tumor formation." (PMID 40301490, 2025). "The high expression of HIF-1α associated with increased proliferation of tumor cells can results in the higher pressure on tumor neovascularization wall, which may slow down the blood flow velocity of local tumor microcirculation and lead to the reduced f value." (PMID 40444079, 2025). "Furthermore, HIF-1α activation is closely associated with tumor migration and invasion, as it can upregulate matrix metalloproteinases (MMPs) and other proteins, facilitating extracellular matrix degradation and increasing tumor cells' invasive and metastatic potential." (PMID 41190142, 2025). "Specifically, HIF1α deficiency in the tumor endothelium reduces the number of tumor vessels, which reduces tumor growth but increases tumor necrosis; roxarsenical (Rox), an organoarsenic compound, has a significant pro-tumor effect in vivo due to its ability to increase HIF-1α." (PMID 38824197, 2024). "In addition, hypoxia-inducible factors 1α (HIF-1α), are often closely associated with tumor progression, and they could promote the acquisition of a malignant phenotype in HCC by activating glycolysis and the transcription of angiogenic cytokines such as VEGF." (PMID 39086383, 2024). "However, it has been reported that hypoxia-inducible factor 1 alpha (HIF-1α) up-regulation caused by hypoxia in the tumor may be a potential driving force for tumor metastasis." (PMID 38771435, 2024). "Hypoxia in the TME significantly contributes to tumor immune escape; HIF-1α causes tumor immune escape by promoting macrophage polarization, inhibiting the recruitment of regulatory T cells, and suppressing the anti-tumor activity and immune cell infiltration of CD8+ T cells." (PMID 38236337, 2024).
tumor (continued). "Besides, higher HIF-1α expression is associated with more significant local tumor hypoxia and decreased blood oxygen content, which can lead to increase in paramagnetic substances like deoxyhemoglobin and iron-containing hemoglobin, resulting in elevated R2* values." (PMID 39723370, 2024). "In addition, HIF-1α hinders the transcriptional ability of c-myc, specifically by competing with c-myc to bind sp1, causing a certain degree of cell cycle arrest and decreasing the proliferation rate of tumor cells." (PMID 38172980, 2024). "Finally, TME induced a purposeful pairing between HIF-1α and NF-κB, suggesting that the synergistic interplay between the two tumor-associated transcription factors is essential for CRC cell malignancy and migration and that CA silences these factors in tandem." (PMID 37583906, 2023). "Moreover, the selective elimination of HIF-1α-positive cells and its downstream effects on tumor metabolism may provide novel insights into the underlying mechanisms of GL treatment development." (PMID 38067241, 2023). "We have previously shown that treatment of GBM cells with CoQ10 acts as a radiosensitizer, targeting the naturally increased tumor-associated mitochondrial reactive oxygen species (ROS) and diminishing the total antioxidant cell capacity by mechanisms involving a reduction in the level of HIF-1α." (PMID 36319818, 2023). "EMT also seems to be linked with the function of miR-205-5p, while miR-210-3p seems to inhibit the tumor growth and metastasis of BC via targeting fibroblast growth factor receptor-like 1 and is also strongly associated with markers of tumor hypoxia like HIF-1α, CA9, Glut-1 protein." (PMID 35365098, 2022). "Therefore, abrogating HIF-1α–mediated immune suppression in tumor cells and tumor-associated myeloid cells may be more important for immunotherapeutic efficacy than preserving HIF-1α function in T cells." (PMID 35239514, 2022). "Thus, prolonged oxidative stress, such as inflammatory conditions, may consume Asc and increase the risk of tumor development through sustained HIF-1α activation." (PMID 36234722, 2022). "A number of studies published in the late 1990s/early 2000s have shown that intracellular generation of reactive oxygen species (ROS) is implicated in the hypoxic stabilization of HIF-1α, providing a possible mechanism through which ROS may promote tumor invasiveness and metastatic spread." (PMID 36354671, 2022). "Agents that target the PI3K/AKT pathway may also prevent the transformation of premalignant gastric lesions into full malignancy, considering the mediator role of the PI3K/AKT/mTOR/HIF-1α axis in tumor-promoting inflammation in H. pylori- and EBV-associated GC." (PMID 35681691, 2022). "Furthermore, Maf, Atf3, and Hif1a are potential regulators of regulatory myeloid (Mreg) cells, while Hif1a is a potential regulator of tumor-associated macrophages in MCA205 mouse tumors; these two myeloid subpopulations share the expression of Arg1 and Trem2 (Arg1+Trem2+)." (PMID 35359989, 2022). "Literature also suggests that genes or signaling pathways regulating cell proliferation may be associated with accelerated tumor progression and a poor prognosis; notable examples include the Notch pathway, hypoxia-inducible factor 1-alpha (HIF1-α), and epidermal growth factor receptor (EGFR)." (PMID 36299463, 2022). "Considering the role of HIF-1α in determining tumor proliferation and invasiveness, as well as the association of high expression of these mesenchymal markers with worse survival of GBM patients, the reduced HIF-1α expression could be associated with a less aggressive GBM progression." (PMID 36295510, 2022). "Bioluminescent monitoring of murine transgenic BC model harboring luciferase underlying VEGFR2 promoter revealed that tumor angiogenesis and growth could be attenuated following by intratumoral injection of anti-miR-21 which is associated to HIF-1α/VEGF/VEGFR2 signaling inactivation." (PMID 35499045, 2022).
tumor (continued). "In addition, primary tumour HIF-1α positivity correlated to an increase in any recurrence in the whole study population and remained an independent risk factor after adjustment for patient age, tumour subtype, size, and systemic treatment." (PMID 35140341, 2022). "Importantly, the cells overexpressing the FH mutant exhibited higher proliferation and extracellular acidification rate value (ECAR) which might be caused by the upregulated HIF-1α indicating the tumor phenotype." (PMID 35163394, 2022). "Moreover, HIF-1α is associated with both inflammation and tumor therapy resistance." (PMID 35799889, 2022). "Tumor hypoxia leads to an aggressive cancer phenotype which facilitates invasion and significantly increases the risk of metastasis; vitamin C acts as a cofactor of selected enzymes (hydrolases), inhibiting the activity of the hypoxia-induced factor 1α (HIF-1α)." (PMID 35215535, 2022). "However, it’s difficult to conclude whether those effects are an isolated consequence of HIF-1α silencing, considering the complex interaction with tumor-associated macrophages as well as other isoforms that were not investigated." (PMID 36139678, 2022). "Indeed, HIF-1α-deficient Tregs exhibit reduction in glycolytic-driven Treg migration and oxidation of fatty acid-driven immunosuppression, which in turn upregulates anti-tumor immune responses of CD8+ TILs." (PMID 33532902, 2021). "Loss of HIF-1α in Tie2+ endothelial cells affects various parameters of endothelial cells, including proliferation, chemotaxis, and wound healing, and causes inhibition of tumor vessel density as well as reduction in tumor growth in a model of lung cancer (Lewis Lung carcinoma (LLC))." (PMID 34202979, 2021). "Furthermore, our results suggest that patients with high levels of HIF1α or HIF2α expression in their primary tumor may be at an increased risk of bone metastasis development." (PMID 34556788, 2021). "Besides tumor hypoxia or pVHL loss, other potential regulators of HIF1α may exist, which remains to be investigated." (PMID 34779768, 2021). "Moreover, via the up-regulated, hypoxia-inducible factor-1α (HIF-1α), hypoxia has also been shown to facilitate immunosuppression and immune escape by activating lymphocytes, myeloid-derived suppressive cells, dendritic cells, and tumor-associated macrophages." (PMID 33535466, 2021). "Moreover, IHC staining using clinical RCC tissues demonstrated that, whereas HIF-1α was expressed in entire tumor tissue including the proximal regions of tumor vessels due to the loss of VHL, SPINK1 expression was predominantly detected in perinecrotic regions distal to blood vessels." (PMID 34747365, 2021). "Moreover, the high expression of hypoxia‐inducible factor‐1α (HIF‐1α), a crucial transcription factor, will cause angiogenesis of tumor tissue and accelerate tumor infiltration, which could easily lead to OM." (PMID 33336932, 2021). "In addition, HIF-1α, a key regulator of the tumour hypoxic response, may be implicated in the signature genes’ association with poor prognosis." (PMID 34616772, 2021). "Stabilized HIF1α alters the function of MDSCs, promoting enhanced expression of inducible nitric oxide synthetize (iNOS) and arginase and promoting their differentiation toward a tumor-associated macrophage (TAM)-like phenotype with the ability to suppress T cell function." (PMID 33923299, 2021). "Further, progranulin tumor expression was significantly linked to histological grade (p< 0.001), where patients with high-grade tumors showed high progranulin expression, in addition to Ki-67 (p=0.001) and the hypoxic marker hypoxia-inducible factor 1-alpha (HIF1α) (p=0.002)." (PMID 33618683, 2021).